IRF5 (interferon regulatory factor 5)
Diseases named in the same sentence as IRF5 in open-access papers (continued):
Sharing a sentence is not in itself a finding about the gene and the disease.
autoimmune disease (continued). "The proposed inclusion of IRF5 in the regulation of T-bet through a conserved interaction with DEF6 in T cells will likely have direct implications in our understanding of the control of cytokine release by T cells and the T cell-driven pathogenesis of several autoimmune diseases." (PMID 32582209, 2020). "We also note that while not much is known about IRF5 and IL23 induction, both are heavily involved in autoimmune diseases and dysregulation of either one substantially increases the risk of an overzealous immune response." (PMID 29896111, 2018). "The most prominent genetic risk factors are alleles within the HLA class, particularly HLA-DRB1, while a large number of non-HLA genes (FLT3, IRF5, STA4) involved in autoimmune diseases are interlinked in a network that regulates IFN signalling and dendritic cell and T cell function." (PMID 40495344, 2025).
viral infection (48 papers, 2009 to 2025). "Irf5−/− mice have increased susceptibility to viral infections, slightly reduced levels of type I IFN in serum, and more significantly reduced levels of pro-inflammatory cytokines." (PMID 23300459, 2013). "Our results demonstrated that the increased susceptibility to viral infection is mediated by epigenetic mechanisms down-regulating key antiviral defense pathway regulators IRF5 and IRF7." (PMID 22194884, 2011). "Individuals with the IRF5 SLE-risk haplotype may have a better immune response to viral infection but may be at higher risk of developing SLE, an aspect of risk compensation." (PMID 37189338, 2023). "Importantly, the K63‐linked ubiquitination of IRF5, required for its nuclear translocation, is an indispensable mechanism in macrophages that mediate metabolic inflammation and loss of glycaemic homeostasis in T2D (independently of viral infection)." (PMID 32816392, 2020). "We also found that the type of viral infection has an impact on IRF5 involvement in mediating IP-10 production." (PMID 40493408, 2025). "Interferon regulatory factor 5 (IRF5) is a transcription factor that plays a role in orchestrating innate immune responses, particularly in response to viral infections." (PMID 40137979, 2025). "Here we show that the transcription factor IRF-5 helps to limit functional exhaustion of murine CD8+ T-cells during the chronic stage of LCMV (CL13) viral infection." (PMID 40494997, 2025). "It is important to note that M1 macrophages in a bronchial asthma model exhibit an anti-inflammatory effect, while showing a proinflammatory effect during bacterial or viral infections, suggesting possible immunomodulatory effects of IRF5 and NR2C2." (PMID 41516283, 2025). "For instance, while the O-GlcNAcylation of RIPK3 and S6K1 attenuates their activity in inflammatory signaling, that of IRF5 exerts the opposite effect and leads to heightened inflammation in viral infection, as we describe below." (PMID 41227388, 2025). "IRF5 is involved in the regulation of cell growth, differentiation, apoptosis, immune system activity, and response to viral infection and is a key factor in promoting the inflammatory macrophage phenotype." (PMID 39624492, 2024). "Interferon-regulatory factor 5 is a crucial transcription factor discovered during the investigation of interferon response to viral infection." (PMID 36010574, 2022). "While lung inflammation induces CD11b expression in AMs, Irf5−/− mice fail to up‐regulate CD11b expression in AMs in response to viral infection, suggesting a defect in AM responses." (PMID 33423291, 2021). "In order to determine the functional consequences of IRF5 controlling AM metabolic phenotype upon viral infection in vivo, adult C57BL/6 WT and Irf5−/− mice were infected with H3N2 IAV." (PMID 33423291, 2021). ", we next assessed how IRF5 controls gene expression of Hk2 and other key metabolism enzyme genes upon viral infection in vivo." (PMID 33423291, 2021). "Using a mouse model of influenza A infection, we have shown that Hk2 gene expression is controlled by IRF5 during viral infection and gene expression levels are decreased in the absences of IRF5." (PMID 33423291, 2021). "After poly(I:C) stimulation to mimic viral infection, both WT and Irf5−/− BMDMs became more metabolically quiescent." (PMID 33423291, 2021). "In the same way that endotoxic shock is abrogated by inhibiting IRF5, “cytokine storm” in viral infection can also be suppressed by IRF5 inhibition, as shown for influenza A." (PMID 33936053, 2021). "Viral infections or agonists of TLR7 or TLR9 can activate IRF5 in DCs in vitro in a MyD88-dependent manner." (PMID 31999809, 2020). "Prior studies have indicated that viral infections of Irf5−/− mice lead to reduced cytokine production in comparison to wild-type (WT) controls." (PMID 32075938, 2020).
viral infection (continued). "The macrophage markers F4/80, macrophage-1 antigen (Mac-1), Iba1 and IFN regulatory factor 5 (Irf5) from M1 macrophages, and jumonji domain containing-3 (Jmjd3) and others from M2 macrophages, were also induced by the viral infection." (PMID 32317718, 2020). "We found that histone deacetylases (HDACs) and HATs CREB-binding protein (CBP)/p300 interact with IRF5 in response to virus infection, and this was required for IRF5 transactivation." (PMID 30515152, 2018). "IKKβ also directly regulates IRF5 (Interferon Regulatory Factor 5), a transcription factor important in the innate immune response to virus infection." (PMID 29292732, 2017). "IRF5 was first identified and characterized as a transcriptional regulator of type I interferon expression after virus infection." (PMID 27481535, 2016). "Upon viral infection, IRF5 is phosphorylated and thereby translocated to the nucleus where it binds to the regulatory regions of its target genes." (PMID 24453413, 2013). "Overall, the loss of IRF-5 in the setting of an IRF-3 and IRF-7 deficiency renders mice more vulnerable to viral infection and early death, approaching that seen in mice that cannot respond to type I IFN." (PMID 23300459, 2013). "IRF5 is involved in various inflammatory processes such as the type I interferon response to virus infection and pathogen recognition receptor signalling." (PMID 24453413, 2013). "Interferon Regulatory Factor 5 is a transcription factor that regulates the expression of genes involved in the response to viral infection and in the stimulation of the immune system." (PMID 22507190, 2012). "Lung cancer cells can be partially protected from viral killing using IRF5+IRF7 overexpression, whereas IFN pathway disruption by transfection of siRNAs to IRF5+IRF7 increases cells' vulnerability to viral infection." (PMID 22194884, 2011). "The transcription factor Interferon Regulatory Factor 5 (IRF-5) has been shown to be involved in the induction of proinflammatory cytokines in response to viral infections and TLR activation and to play an essential role in the innate inflammatory response." (PMID 21253574, 2011). "Although IRF-5 has been shown to have a major impact on the innate immune response to viral infections, its role in shaping the development of adaptive Th1 responses has not been previously demonstrated." (PMID 21253574, 2011). "By promoting IRF5 expression and its transcriptional activity, vitamin D may prime macrophages to mount a robust early induction of ISGs upon viral infection." (PMID 40839599, 2025). "In addition to regulating the expression of proinflammatory cytokine responses to microbial and viral infection, evidence of IRF5 as a metabolic transcriptional regulator is emerging." (PMID 37189338, 2023). "IRF7 can also dimerize with IRF5 through the DNA-binding domain after viral infection." (PMID 34506605, 2021). "As the human IRF5 has been associated with promoting macrophage activity and polarization to T helper type 1 (Th1)/Th17 response, this indicates that BRO positively supports the innate immune response to clear the viral infection." (PMID 31067687, 2019). "IRF5 has also been shown to play critical roles during viral infection." (PMID 30515152, 2018). "Unfortunately, we were also unable to determine whether overexpression of MYC could restore ASC differentiation in IRF5 knockdown cells due to limitiations in transfection and/or viral infection efficiency." (PMID 29367853, 2017). "In view of the putative role of viral infection in pathogenesis of SMZL and recent finding of activating mutations in MYD88 (an adaptor in TLR signalling) in SMZL, we investigated whether IRF5 was targeted by mutation." (PMID 23028731, 2012). "However, two Nuclear Localization Signals and a Nuclear Export Signal regulate IRF5 subcellular localization, promoting its nuclear import after viral infection." (PMID 22507190, 2012). "Activation of IRF5 in response to viral infection has been controversial." (PMID 22412986, 2012).
viral infection (continued). "In addition to its role(s) in autoimmune and viral disease pathogenesis, the past 5–10 years has brought about a plethora of new data implicating IRF5 in multiple other diseases, including cancer, obesity, neuropathic pain, cardiovascular, and metabolic dysfunction." (PMID 30515152, 2018). "IRF5 knockout mice were reported to be susceptible to viral infections, while, the expression levels of type I IFNs and other pro-inflammatory cytokines including tumour-necrosis factor (TNF)-α, interleukin (IL)-6 and IL-12, were reduced in response to viral infections." (PMID 27350041, 2016). "Within the IRF family of transcription factors, IRF3, IRF5, and IRF7 have well-described roles in mediating antiviral and inflammatory responses downstream of diverse viral infections." (PMID 40493408, 2025). "During viral infection, miR-146a-5p suppresses the production of type-I interferon by targeting not only IRAK2, TRAF6, and IRAK1 but also STAT-1 and IRF-5." (PMID 38787176, 2024). "Interferon regulatory factor 5 (IRF5) is a key transcription factor involved in regulating the expression of proinflammatory cytokine responses to microbial and viral infection and macrophage phenotype." (PMID 33423291, 2021). "TRIM21 mediates the polyubiquitination and degradation of the DNA sensor DDX41 and the IRF transcription factors IRF3, IRF5, and IRF7 to negatively regulate the production of interferon-β during viral infection." (PMID 33061806, 2020). "IRF5 can be phosphorylated by IKKβ which leads to homo-dimerization and nuclear translocation to induce IFN activation following viral infection." (PMID 30515152, 2018). "Interferon regulatory factor 5 (IRF5) is a key transcription factor of innate immunity, which plays an important role in host restriction to viral infection and inflammation." (PMID 28578407, 2017). "The authors demonstrated that TLR activation through IRF5 (bacterial infection) induced high levels of IL-12 and low levels of IFN-I whereas RLR activation through IRF3 (viral infection) induced high levels of IFN-I and low levels of IL-12." (PMID 23157617, 2012). "Recent studies have suggested that IRF-5 can activate transcription of IFN and other inflammatory cytokine genes after viral infection or TLR stimulation." (PMID 19798431, 2009). "In some virus infections, the antiviral effect is independent of IFN-I, IRF3, IRF5 or IRF7, and deficient mice survive the infection." (PMID 37737190, 2023). "The host immune targets such as TLR7, IRF7, IRF5, and IL6, which are involved in the immune response against viral infections, and the sex-specific targets such as AR and ESSR were taken to investigate any possible link with the SARS-CoV-2 host receptors ACE2 and TMPRSS2." (PMID 36992366, 2023). "Interferon regulatory factor 5 (IRF5) is a master regulator of macrophage phenotype and a key transcription factor involved in expression of proinflammatory cytokine responses to microbial and viral infection." (PMID 33423291, 2021). "In addition to IRF3, other IRFs have been involved in the amplification of type I IFN response following viral infection: IRF7 plays an instrumental role whereas IRF1 and IRF5, are reported to be dispensable for inducing type I IFN." (PMID 31319869, 2019). "Our studies indicate that viral infection with Newcastle Disease Virus (NDV) does not activate IRF5, although expression of kinases that function during viral infection, TBK-1 or NF-κB kinase-ε (IKKε), can phosphorylate IRF5." (PMID 22412986, 2012). "Moreover, Irf5 knockout accelerated TMEV infection in cochlear sensory epithelia, suggesting that Irf5-mediated macrophage polarization is required for efficient protection against virus-infection." (PMID 32317718, 2020). "Although IRF-5 was originally identified as an inducer of inflammatory cytokines (IL-6 and TNF-α) downstream of TLR-7 and MyD88 signaling, subsequent studies suggested that it could contribute to type I IFN production after viral infection." (PMID 23300459, 2013).
viral infection (continued). "However, IRF5 and IRF7 overexpression is not sufficient to completely restore IFN pathway and only partially rescued cells from viral infection due to deficiency of other important ISGs." (PMID 22194884, 2011). "IRF1, IRF5, and IRF7 can induce the expression of IFIT and IFITM proteins in the absence of viral infections." (PMID 32499867, 2020). "Indeed, lack of IRF-5 expression in genetically modified Irf5-/- mice resulted in attenuation of Type I IFN, TNFα and IL-6 production in response to viral infection." (PMID 21253574, 2011). "The decrease in expression of pGL3-PURA in the presence of overexpressed IRF-3, IRF-5, and IRF-7 and the specific binding of IRF-3 to sequence near TSS II led us to investigate whether or not viral infection could affect PURA transcription." (PMID 21062477, 2010).
rheumatoid arthritis (46 papers, 2008 to 2025). A chronic, systemic autoimmune disorder characterized by inflammation in the synovial membranes and articular surfaces. "A meta-analysis study showed that the SNP rs2004640, a variant of the IRF5 gene, was associated with rheumatoid arthritis especially when the dominant genetic model was applied." (PMID 40531670, 2025). "It has already been demonstrated that the genetic variant rs2004640, which is located in exon 1 of the IRF5 gene, results in functional modifications that affect the expression of messenger RNA, increasing the risk of developing rheumatoid arthritis." (PMID 40531670, 2025). "Recently, polymorphisms in the IRF5 gene have been found to associate with an increased risk of developing rheumatoid arthritis, lupus erythematosus and inflammatory bowel diseases." (PMID 34950033, 2021). "IRF5 is responsible for M1 macrophage polarization, it is implicated in sterile inflammation and auto-immunity, namely rheumatoid arthritis where risk-variants contributing to the over-expression of IRF5 have been reported." (PMID 32140136, 2020). "Recent studies in SLE and Rheumatoid Arthritis (RA), concluded that disease-associated atherosclerosis is mediated through IRF5." (PMID 31178872, 2019). "The PTV rs2004640 in IRF5 has previously been associated with rheumatoid arthritis and has been connected to pathogenesis in the mouse model." (PMID 29691392, 2018). "There has been no previous specific mention of rs17424179, but rs3807306 has been found to account for most haplotype effects in SLE association among African Americans, and it has been highlighted among the IRF5 polymorphisms particularly associated with multiple sclerosis and rheumatoid arthritis." (PMID 21627826, 2011). "TLR7 induced IL-1β production in synovial fibroblasts and M1-type macrophage from rheumatoid arthritis patients was also in an IRF5-dependent manner." (PMID 34950033, 2021). "Whilst it is difficult to dissect the biological meaning of statistical epistatic models, it should be noted that several lines of evidence support a role for Fcγ receptors and IRF5 in rheumatoid arthritis and TNF driven processes." (PMID 20691091, 2010). "In our study, there were six novel loci outside of this region where genetic variation may influence rheumatoid arthritis risk via changes in DNA methylation (TTC34, MMEL1, AFF3, IRF5, CXCR5 and PGAP3)." (PMID 29893838, 2018). "Interferon regulatory factor 5 (IRF5) polymorphism has been shown to be a risk factor for the development of SLE, rheumatoid arthritis (RA), multiple sclerosis (MS), Sjögren's syndrome and inflammatory bowel disease." (PMID 20479942, 2010). "Besides SLE, IRF5 is involved in the pathogenesis of other immune diseases, such as rheumatoid arthritis (RA), Sjögren's syndrome, and inflammatory bowel disease." (PMID 28525378, 2017).